CDK6 (cyclin dependent kinase 6)
Diseases named in the same sentence as CDK6 in open-access papers (continued):
Sharing a sentence is not in itself a finding about the gene and the disease.
osteosarcoma (continued). "Alterations in the Rb/p16 pathway could indicate that osteosarcoma cells are vulnerable to CDK4/CDK6 inhibitor treatment." (PMID 34921235, 2022). "CDK6 was also upregulated in the 3 osteosarcoma cell lines without RB1 mutations: 143B, SJSA-1 and U-2 OS." (PMID 30220967, 2018). "Taken together, our results highlight an important role for miR-29b in the regulation of CDK6 in osteosarcoma and may open new avenues for future osteosarcoma therapies." (PMID 27230400, 2016). "Therefore, miRNAs are likely to play a biologically relevant role in regulating CDK6 expression in osteosarcoma." (PMID 27230400, 2016). "Finally, we examined the function of miR-29b-driven repression of CDK6 expression in osteosarcoma cells." (PMID 27230400, 2016). "Interestingly, we observed that the restoration of CDK6 expression can successfully attenuate the anti-proliferation and anti-migration effects of miR-29b on osteosarcoma cells, although miR-29b has many other targets." (PMID 27230400, 2016). "In addition, by overexpressing miR-29b in osteosarcoma cells, we experimentally validated the direct inhibition of CDK6 translation by miR-29b." (PMID 27230400, 2016). "Because CDK6 is essential for the regulation of cell proliferation, we evaluated whether miR-29b would modulate cell proliferation via binding to CDK6 in osteosarcoma cells." (PMID 27230400, 2016). "Moreover, the potential role of miR-29b as a tumor suppressor of osteosarcoma through targeting CDK6 in the processes of proliferation and migration has been experimentally validated." (PMID 27230400, 2016). "Finally, we showed that miR-29b inhibited CDK6 expression and consequently inhibited proliferation and migration in cultured osteosarcoma cells." (PMID 27230400, 2016). "Furthermore, we identified an inverse correlation between miR-29b and CDK6 protein levels in osteosarcoma tissues." (PMID 27230400, 2016). "We first determined the expression patterns of CDK6 in osteosarcoma tissues." (PMID 27230400, 2016). "This suggests that CDK6 may be an important downstream effector of circPRMT5 in osteosarcoma." (PMID 38626179, 2024). "Thus, our data support previous findings that CDK4/CDK6 inhibition might be a new targeted treatment strategy for osteosarcoma patients." (PMID 34921235, 2022). "Furthermore, we demonstrate that the defective cell cycle regulation pathway caused by p16INK4A inactivation can be therapeutically exploited using the selective CDK4/CDK6 inhibitor palbociclib in both 2D and 3D in vitro culture models of osteosarcoma cell lines." (PMID 34921235, 2022). "However, little is known about the expression and function of CDK6 in osteosarcoma." (PMID 27230400, 2016). "We next investigated whether miR-29b was inversely correlated with CDK6 in osteosarcoma." (PMID 27230400, 2016). "In conclusion, our results revealed that circPRMT5 promotes osteosarcoma malignant activity by recruiting CNBP to facilitate the translation and stability of CDK6 mRNA." (PMID 38626179, 2024). "More recent studies indicated CDK6 and EGFR contribute to the development of chemotherapy resistance in osteosarcoma." (PMID 37894336, 2023). "MiR‐145‐5P inhibits osteosarcoma cell proliferation by targeting inhibit of E2F3b, which affected Cyclin D1, CDK2, CDK4 and CDK6 expression." (PMID 34741389, 2021). "In order to confirm that increased CDK4 and CDK6 activity results in RB hyperphosphorylation and leads to overexpression of HELLS, we treated all four human osteosarcoma cell lines with CDK4/6 inhibitor, palbociclib." (PMID 30220967, 2018). "However, the function and regulation of CDK6 in osteosarcoma is still largely unknown." (PMID 27230400, 2016). "Furthermore, we found that silencing CDK6 expression using siRNA could inhibit proliferation and migration of osteosarcoma cells, whereas overexpressing CDK6 induced opposing effects, validating its role as an essential oncogene during osteosarcoma tumorigenesis." (PMID 27230400, 2016).
osteosarcoma (continued). "Notably, three transcriptional modules out of the top ten MRs, CDK6, EGFR and PANX3, have already been proven to be critical mediators of pathogenesis in osteosarcoma." (PMID 37894336, 2023). "Indeed, using two-dimensional (n = 7) and three-dimensional (n = 3) cultures of human osteosarcoma cell lines, it was shown that osteosarcoma cells with defective p16INK4A are sensitive to the CDK4/CDK6 inhibitor palbociclib after 72-hour treatment." (PMID 34921235, 2022). "In osteosarcoma tissue, the expression of LOC100129620 was negatively correlated with the expression of miR-335-3p, while the expression of LOC100129620 was positively correlated with the expression of CDK6." (PMID 34015762, 2021). "Moreover, many MYC bound super enhancer genesincluding CDK6, TGFB and CALM2 are downregulated upon THZ1 treatment, further confirming that role of THZ1 in targeting super enhancer signaling in osteosarcoma." (PMID 29644114, 2018). "To assess the mechanism through which the RB-E2F pathway is being deregulated in the osteosarcoma cell lines without RB1 mutations, we analyzed CDK4 and CDK6 gene expression." (PMID 30220967, 2018). "We found that CDK6 protein level, rather than CDK6 mRNA level, is much higher in osteosarcoma tissues than in normal adjacent tissues, which indicates a post-transcriptional mechanism involved in CDK6 regulation in osteosarcoma." (PMID 27230400, 2016). "In this study, we first showed that CDK6 protein levels were significantly higher in 6 pairs of osteosarcoma tissues than in corresponding noncancerous tissues." (PMID 27230400, 2016). "In conclusion, the results of bioinformatics prediction taken together with the inverse correlation between miR-29b and CDK6 protein levels, but not mRNA levels, indicated that CDK6 is a target of miR-29b in human osteosarcoma tissues." (PMID 27230400, 2016). "In this study, we found that CDK6 protein levels, but not mRNA levels, were upregulated in osteosarcoma tissues." (PMID 27230400, 2016). "Additionally, about 20–23% of primary osteosarcoma biopsies showed intact Rb protein but defective p16INK4A or CDK4/CDK6 overexpression, indicating that CDK4/CDK6 inhibition could benefit a subset of patients." (PMID 40563473, 2025). "Therefore, our study indicates that the resting dendritic cell signature constructed by AOC3, CDK6, COL22A1, and RNASE6 may contribute to predicting osteosarcoma prognosis and thus therapy guidance." (PMID 36189307, 2022). "Our results illustrate that loss of CDKN2A and/or CDKN2B are early events in the development of osteosarcoma, and that these events can be targeted by CDK4/CDK6 inhibition, which might be used as a novel therapeutic option in approximately 20–23% of the patients." (PMID 34921235, 2022). "Interestingly, CDK6 mRNA levels in human osteosarcoma tissues were not significantly different from CDK6 mRNA levels in corresponding noncancerous tissues." (PMID 27230400, 2016).
cervical carcinoma (25 papers, 2012 to 2024). A carcinoma arising from either the exocervical squamous epithelium or the endocervical glandular epithelium. "Our results suggested the relationships between CDK6 3'UTR polymorphisms and cervical cancer pathogenesis, and the involvement of CDK6 in cervical cancer development among Uyghur females." (PMID 30829464, 2019). "This study first demonstrated the relationships between the 3'UTR variants in CDK6 gene and cervical cancer susceptibility in Uyghur females from Xinjiang Uyghur Autonomous Region of China." (PMID 30829464, 2019). "The genotypes of the six CDK6 variants (rs8179, rs42032, rs42033, rs42034, rs42035, and rs42038) were identified among 306 cervical cancer cases and 310 healthy controls with the Agena MassARRAY platform." (PMID 30829464, 2019). "Despite the limitations, our research first validated the involvement of CDK6 in the pathogenesis of cervical cancer, and discovered the associations of CDK6 variants with cancer risk in Uyghur population." (PMID 30829464, 2019). "The aim of this study was to evaluate the effects of CDK6 3' untranslated region (3'UTR) polymorphisms on cervical cancer susceptibility among Uyghur females." (PMID 30829464, 2019). "Accordingly, further well‐designed studies should be considered to improve the understanding of the roles of CDK6 and its polymorphisms in cervical cancer among Uyghur females." (PMID 30829464, 2019). "The relationships between the CDK6 variations and cervical cancer risk were evaluated in a Uyghur representative group." (PMID 30829464, 2019). "In this study, a case‐control study was carried out in order to investigate the potential impact of the polymorphisms in CDK6 3'UTR on individual susceptibility to cervical cancer, which is still an obvious public health threat to Uyghur females from Xinjiang province, China." (PMID 30829464, 2019). "Therefore, our findings directed the next step for the mechanism study of CDK6 polymorphisms in cervical cancer." (PMID 30829464, 2019). "CDK6 rs8179 and rs42033 were correlated to the decreased risk of cervical cancer in Uyghurs under the allele model (rs8179 and rs42033: OR = 0.60, 95% CI: 0.37–0.99, p = 0.043) and log‐additive model (rs8179 and rs42033: OR = 0.62, 95% CI: 0.38–1.00, p = 0.047)." (PMID 30829464, 2019). "The mRNA expression levels of CCND1, CCNE1, CDK2, CDK6, and p21CIP1 were significantly related to the histological classification of cervical cancer (p < 0.05)." (PMID 35246013, 2022). "Collectively, these results suggest that CDK6 overexpression in EphA2 knock‐down cells restores oncogenic activity of the cervical cancer cells." (PMID 33586348, 2021). "Previous studies have demonstrated that treatment with Astragalus-containing CHM (SH003) reduces the levels of expression for G1 phase-related CDK (CDK2, CDK4, and CDK6) and cyclin D and induces extrinsic cell apoptosis in HeLa cervical cancer cells." (PMID 34393766, 2021). "A recent study indicated that miR-636 suppressed cell survival of cervical cancer by targeting CDK6/Bcl-2." (PMID 33472614, 2021). "As a transcriptional regulatory factor, CDK6 mediated cell-stimulation effect of IL-1 jointly with NF-κB in cervical cancer cells." (PMID 32047552, 2020). "Cyclin dependent kinase 6 (CDK6) plays a crucial role in malignant tumor whereas less is reported in cervical cancer development." (PMID 30829464, 2019). "The mRNA levels of CDK6 were examined in cervical cancer tissues from Uyghur patients and normal cervix samples." (PMID 30829464, 2019). "Research on the susceptible SNPs is an important step towards the understanding of the CDK6 in cervical cancer development." (PMID 30829464, 2019). "Recently, it has been shown that EX-527 and AGK2 decrease Hela cervical cancer cell proliferation associated with G1 phase arrest and the downregulation of CDK4 and/or CDK6." (PMID 29401749, 2018).
cervical carcinoma (continued). "The effects of knockdown of ClC-3 expression by ClC-3 siRNA on cell cycle progression and expression of cyclin D1, CDK4, CDK6, p21 and p27 were also tested in the HeLa cell, a cell line derived from cervical cancer cells." (PMID 27451945, 2016). "This demonstrates that miR-145 inhibited the mRNA and protein expression of CDK6 in the HeLa cervical cancer cells at the transcriptional and translational levels." (PMID 25009625, 2014). "The present study aimed to investigate the effect of the inhibition of miR-145 on cyclin-dependent protein kinase 6 (CDK6) and the proliferation of human cervical carcinoma cells." (PMID 25009625, 2014). "Noteworthy, CDK6 has also been shown to be a direct miR-29 target in mantle cell lymphoma, acute myeloid leukemia and cervical cancer." (PMID 23245396, 2012). "Therefore, we aimed to study the effect of circRNA CDK6 (circCDK6) on the development and biological behavior of cervical cancer." (PMID 35152839, 2022). "In addition, there was a significantly correlation between EphA2 protein and CDK6 protein expression in human cervical cancer tissues." (PMID 33586348, 2021). "In conclusion, p16 promotes proliferation in cervical carcinoma cells through CDK6-HuR-IL1A axis." (PMID 32047552, 2020). "The in‐depth genetic information obtained from the findings could not only enhance our comprehension of the CDK6 in cervical cancer, but provide new targets for cancer assessment, prevention and prognosis in Uyghur population." (PMID 30829464, 2019). "These SNPs indicated the outstanding importance of CDK6 in high‐grade cervical cancer, and could be employed as clinical predictors for developing the high‐grade tumor among Uyghur females." (PMID 30829464, 2019). "Interestingly, significant down‐regulation of CDK6 appeared in cervical cancer cases, which suggested the suppression effects of CDK6 during tumor development." (PMID 30829464, 2019). "Additionally, our results also revealed an abnormal expression of CDK6 in cervical cancer patients with Uyghur descent." (PMID 30829464, 2019). "In the present study, an miR-145 expression vector was constructed using the eukaryotic expression vector pcDNATM6.2-GW, and was transfected into HeLa cervical cancer cells to examine the regulatory effect of miR-145 on its downstream target gene cyclin-dependent protein kinase 6 (CDK6)." (PMID 25009625, 2014). "This suggests that miR-145 may directly target the expression of CDK6 to inhibit the proliferation of cervical cancer cells." (PMID 25009625, 2014). "In summary, the expression of pcDNA6.2-GW-miR-145 downregulated the expression of CDK6 and inhibited the proliferation of HeLa cervical cancer cells, providing a basis for the further study of the effects of miR-145 on the biological behaviors of cervical cancer cells and the associated mechanisms." (PMID 25009625, 2014). "The proteins YY-1 and Cyclin Dependent Kinase 6 (CDK6) and Heat-shock protein 47 (HSP47) are regulated in Steps 1 and 4, respectively, arguing a fine-tuning regulation of miR-29a and -b in cervical cancer progress." (PMID 28216603, 2017). "The proteins YY-1 and CDK6 are upregulated in CIN 1 and cervical cancer, respectively, by miR-29a and miR-29b, showing a fine-tuning regulation in the cervical carcinoma progress." (PMID 26057746, 2015). "Clinical evidence also shown that the decreased expression of miR-29a in high-grade cervical cancer lesions and YY1 and CDK6 as downstream targets of miR-29a may contribute to unchecked cellular proliferation and resistance to apoptotic stimuli in HeLa cells." (PMID 35628336, 2022).
non-small cell lung carcinoma (25 papers, 2011 to 2025). A group of at least three distinct histological types of lung cancer, including non-small cell squamous cell carcinoma, adenocarcinoma, and large cell carcinoma. "For instance, in copy number omics, we discover pathways corresponding to genes like EGFR, CDK6, RASSF5, BRAF, and CCND1, which are associated with non-small cell lung cancer." (PMID 40191608, 2025). "Supporting this observation, previous studies have shown that miR-107 directly targets CDK6 and induces the cell cycle G1 arrest in gastric, bladder, and non-small cell lung cancer cells." (PMID 37744274, 2023). "CDK6 was involved in the occurrence, development and metastasis of non-small-cell lung cancer by regulating cell cycle and cell proliferation." (PMID 33996561, 2021). "Some research indicates that miR-137 inhibits Cdc42 and Cdk6 expression to suppress the development of non-small cell lung cancer (NSCLC)." (PMID 33413360, 2021). "The present study confirmed that the protein expression of Cyclin D1, CDK6 and Bcl-2 were reduced by overexpression of miR-34a, which is consistent with previous studies in non-small cell lung cancer A549 cells and neuroblastoma NLF cells." (PMID 25268950, 2014). "Guo has reported that FOXD3-AS1 is overexpressed in non-small cell lung cancer, and FOXD3-AS1 upregulation promotes the tumor progression by regulating the miR-135a-5p/CDK6 axis in non-small cell lung cancer." (PMID 36693876, 2023). "For example, CDK6 was recognized as a target of lncRNA HNF1A-AS1/miR-149-5p axis in the modulation of cell proliferation, cell cycle, invasion, and migration of non-small cell lung cancer cells." (PMID 32310823, 2020). "The enriched “non-small-cell lung cancer” pathway included downregulated RB1 and CDK6, well-known tumor suppressors that regulate cell division and the cell cycle." (PMID 30404194, 2018). "The genes included the pathway non-small cell lung cancer were E2F2, E2F3, TGFA, PRKCG, CDK6, EGF, and CDK4, which were all expressed at significantly higher levels in LUSC tissues in comparison to that in the non-cancer group." (PMID 29394946, 2018). "This in turn leads to reduction in the protein levels of cyclin D1 (CCND1) and cyclin-dependent kinase 6 (CDK6), which regulates the phosphorylation of retinoblastoma protein (pRb), as seen in non-small-cell lung cancer cells." (PMID 22102859, 2011). "Furthermore, circRNA C190 overexpression facilitated the proliferation, and migration of non-small cell lung carcinoma (NSCLC) cell lines by targeting CDK1 and CDK6 via sequestrating miR-142-5p." (PMID 36059609, 2022). "We previously reported that SFN-Cys might activate 26S proteasome in human non-small cell lung cancer cells, thus CDK4/CDK6 might be degraded by the ubiquitin-proteasome pathway." (PMID 32860670, 2020).